YBX1 (Y-box binding protein 1)
Diseases named in the same sentence as YBX1 in open-access papers (continued):
Sharing a sentence is not in itself a finding about the gene and the disease.
tumor (continued). "The mRNA levels of YBX1 and SNRPE were increased in tumor samples in the two microarrays, although the expression levels only showed statistically significant differences in GSE19750." (PMID 33101358, 2020). "In line with the role of YB-1 in clonogenic activity, YBX1 knockout inhibited tumor growth after inoculation with MDA-MB-231 cells throughout the 30 days of observation." (PMID 33003386, 2020). "The results showed that YBX1 and LC3I/II co-highly expressed in tumor cell lines or NSCLC tissues compared to their corresponding adjacent normal cells or normal tissues." (PMID 32561752, 2020). "They further showed that luteolin exerts its anti-tumorigenic action by blocking the phosphorylation of YBX1 by RSK, leading to reduced growth of triple-negative breast cancer cells as well as its tumor-initiating cells." (PMID 33375283, 2020). "The apparent discrepancy between the tumor suppressive function of GAS5 and GAS5-mediated translational upregulation of the oncogene YBX1 remains unanswered and also warrants further study." (PMID 31632972, 2019). "Silencing of YBX1 using siRNA decreased the expression of MAPK1 and phosphorylated MAPK154 involved in several tumor related processes including invasion." (PMID 31358880, 2019). "To further confirm the functional correlation between YBX1 and G3BP1 in vivo, we performed xenograft tumor experiments." (PMID 31481087, 2019). "The results showed that YBX1 or G3BP1 overexpression significantly (p < 0.01) promoted tumor cell migration and invasion in RCC ACHN cells, while SPP1 depletion strongly attenuated the effect of YBX1 or G3BP1 induced RCC cells migration and invasion." (PMID 31481087, 2019). "For example, MES GBMs (red arrows) were enriched for CAV1, CD44, CD63, RAB27A, SDCBP and SMPDL3A, while PN (blue arrows) tumours contained higher levels of transcripts for ANXA6, CD81, hnRNPA2B1, YBX1 (RNA binding proteins) and RAB35." (PMID 30034643, 2018). "To further explore YBX1 and tumorigenesis, we next subcutaneously injected 1 × 106 MDCK, MDCKYBX1, or 21D1 cells into NOD/SCID mice, and monitored tumour growth." (PMID 25980435, 2015). "We report YBX1 as an oncogenic modulator which enhances EMT progression and angiogenesis through regulation of the tumour microenvironment." (PMID 25980435, 2015). "Mechanistically, CBX8 interacts with Y-box binding protein 1 (YBX1) to regulate the cell cycle through modulation of Cyclin D1 expression, thereby promoting proliferation in SK-Hep-1, Huh7, and MHCC-97H cells and supporting tumor development in mouse models." (PMID 40175347, 2025). "YBX1 knockdown inhibits PD-L1 expression, restores functional cytotoxic CD8+ T cells, reduces MDSC and regulatory T cell infiltration, reverses chemoresistance, and reinstates anti-tumor immunity." (PMID 41346602, 2025). "The model includes seven key genes—SNX5, YBX1, GNPD1, RAB32, TPM3, ATP6V0B, and RAB7A—which may be involved in tumor growth, immune escape, and microenvironment remodeling and may serve as potential targets for therapy." (PMID 41031219, 2025). "Therefore, NEK6 regulates CDK2 and Bcl-2 through YBX1, which synergizes with CDK4/6 inhibitors to inhibit tumor growth." (PMID 41560755, 2025). "Our findings uncover a novel mechanism that diverges from the well‐established role of YBX1 in transcriptional regulation via nuclear LLPS, which may be related to tumor heterogeneity." (PMID 39976088, 2025). "Furthermore, the extracellular vesicle NSUN2 derived from DLBCL cells promoted tumor growth by positively regulating PDL1, stabilizing it in a YBX1-dependent manner, promoting tumor immune escape and M2 macrophage polarization." (PMID 41462962, 2025). "Disrupting YBX1’s influence on ECM construction could impair the supportive scaffold, hindering tumor cell behavior." (PMID 38255791, 2024).
tumor (continued). "Three potential binding proteins, including YBX1, YBX2 and PHB2, were selected for further validation considering their molecular weights, protein scores, subcellular localizations and potential involvement in tumour metastasis and progression." (PMID 37929660, 2024). "Additionally, we assessed the tumor microenvironment, immune checkpoint-related genes, immunomodulators, Tumor Immune Dysfunction and Exclusion (TIDE) score and drug resistance of ALYREF and YBX1." (PMID 38238581, 2024). "In addition, reports have shown that GAS5 interacts with some proteins, such as E2F1, E2F4, YBX1, EZH2, and YAP, which inhibit tumor progression." (PMID 38782769, 2024). "YBX1 acts as a 5mC reader and recruits ELAV-Like RNA Binding Protein 1 to stabilize HBGF (Heparin Binding Growth Factor) mRNA, thus facilitating metastatic tumor progression." (PMID 38255791, 2024). "Its regulatory role in tumor-associated genomes has garnered considerable attention, and hyaluronic acid can induce nuclear translocation of YBX1, promoting transcriptional activation of MDR1 and expression of membrane p-gp, thereby influencing the efficacy of tumor immunotherapy drugs." (PMID 39727969, 2024). "Overall, MYC showed a trend of increased frequency of positive expression in recurrent/metastatic FN RMS, and YBX1 was expressed in all primary and metastatic FN and FP RMS tumor tissue samples examined, suggesting that MYC and YBX1 play a role in both primary and recurrent/metastatic RMS tumors." (PMID 37345125, 2023). "Similarly, YBX1 has been shown to induce the migration of LUAD cells and contribute to tumor metastasis." (PMID 38008419, 2023). "It should be noted that total YBX1 expression did not significantly differ between p-YBX1Lo and p-YBX1Hi tumours, underscoring the impact of YBX1 phosphorylation on patient outcomes." (PMID 36949044, 2023). "Further, we employed SCENIC to predict transcription patterns of tumor cells, finding a series of key TFs of HCC tumorigenesis, such as TFs in regulation of cell dedifferentiation (SPI1, HMGB3, and YBX1) and in abnormal bile acid metabolism (NR1H4, NR1I3, FOXA3 and DDIT3)." (PMID 37985711, 2023). "Marked hyperactivation of PI3K signalling was observed in the tumours along with expression of the cell proliferation markers Ccnd1 and pMet, the epithelial marker Cdh1 and the phosphorylation of Ybx1, but not the p-EMT marker Pdpn." (PMID 36949044, 2023). "Residual tumours from SCC25 –YBX1 were confirmed negative for YBX1 by immunohistochemistry (IHC) staining." (PMID 36949044, 2023). "When YBX1−/− AsPC-1 cells transfected with NLS-YBX1, NES-YBX1 or NLS-GSDME were inoculated into the pancreas of mice, the transfection of NES-YBX1 or NLS-GSDME barely rescued YBX1−/− tumour cells to allow tumour growth." (PMID 35292781, 2022). "The EdU and transwell assay showed that the exogenous YBX1 regained the proliferation and migration ability of A549 cells, and inhibiting NF-κB signaling with IMD-0354 resulted in drastically reduced YBX1 induced tumor progression." (PMID 35410432, 2022). "In addition, YBX1 knockout can reverse HCC drug resistance by blocking PD-L1 expression and activating T cells in a tumor microenvironment." (PMID 35365216, 2022). "The results are consistent with our in vitro findings, showing a strong negative correlation between SIAH1 and YBX-1 in tumor tissues." (PMID 35273154, 2022). "We identified that YBX1 was overexpressed in TNBC cells, whereas suppression of YBX1 in TNBC cells downregulated glycolytic and EMT gene expressions, and this was accompanied by inhibition of tumor migration and invasion." (PMID 34440660, 2021). "The mouse xenograft model proved that YBX1 and MUC1 affected tumor volume and weight in vivo." (PMID 34976785, 2021).
tumor (continued). "Considering that FOXK1 was reported to be associated with M2-type macrophages attraction and thus promoted tumor growth, the HUMT/YBX1/FOXK1 axis might also be functioning in immune escape." (PMID 32138762, 2020). "MiR-216a acts as an tumor suppressor in SCLC by targeting and downregulating the anti-apoptotic protein B-cell lymphoma 2 (Bcl-2), although it is likely that these effects are also, in part, due to YBX1 downregulation." (PMID 31632972, 2019). "Y-box binding protein 1 (YBX1) is an oncoprotein that binds to the Y-box motif of gene promoters, and its overexpression in HBC is related with more aggressive tumours, poor prognosis, relapse and drug resistance, indicating its potential as a prognostic biomarker." (PMID 31461477, 2019). "Moreover, we found the nuclear expression levels of YBX1 in RCC tissues were correlated with T stage and tumor metastasis." (PMID 31481087, 2019). "The tumor-promoting effects of ILK, in part, is attributable to its ability to phosphorylate Ser473-Akt and GSK3β, as well as to induce the expression of the oncogenic transcription/translation factor Y-box binding protein 1 (YB-1)." (PMID 25821081, 2015). "Given that MDCK cells do not form a tumour xenograft, this finding demonstrates that increased expression of YBX1 can increase the tumourigenic potential of these cells." (PMID 25980435, 2015). "While the relationship with mutation burden was heterogeneous across tumour types, this pattern suggests that links between YBX1 expression and chromosomal instability primarily reflect shared proliferative and mitotic tumour biology rather than an independent genomic instability programme." (PMID 42196325, 2026). "Furthermore, our presented findings suggest that NSUN2 promotes tumor growth and metastasis by increasing ALYREF/YBX1-mediated YAP expression in NSCLC and effective inhibition of m5C modification might provide a potential treatment strategy for NSCLC." (PMID 41794778, 2026). "Moreover, in bladder cancer, YBX1 promotes glycolysis by up-regulating the expression of glycolytic enzymes, glucose uptake, lactate secretion, and the extracellular acidification rate (ECAR), thereby promoting tumor growth." (PMID 40799245, 2025). "YBX1 has been identified as a key RNA-binding protein that selectively sorts miRNAs into exosomes, while HNRNPA2B1 directly regulates RNA cargo loading through post-translational modifications and has been validated by CRISPR knockout approaches in tumor models." (PMID 41462674, 2025). "Additionally, YBX1 reads m5C PEBP1 (Phosphatidylethanolamine Binding Protein 1) mRNA in clear cell renal cell carcinoma and 5mC keratin 13 mRNA in gynecologic cancers, preventing their decay, which contributes to tumor progression." (PMID 38255791, 2024). "The expression of YBX1 in DAPI+ cells (r = −0.2739, P = 0.0098) or in TAGLN2+YBX1+ cells (r = −0.2286, P = 0.0322) was negatively correlated with the percentage of CD8+ cells in the tumor region but positively correlated with the percentage of PDL1+ cells (r = 0.2502, P = 0.0187)." (PMID 39168971, 2024). "Overexpression of ALYREF and YBX1 was accompanied by the upregulation of immune checkpoint inhibitors (such as CD276 and PDCD1) and downregulation of immune checkpoint stimulants (such as CX3L1, ITGB2, CD40LG and SELP), which promoted evasion of immune surveillance by these tumor cells." (PMID 38238581, 2024). "Furthermore, YBX1 phosphorylation at Ser102 by the PI3K signalling was recently shown to positively correlate with the expression of EGFR to facilitate cell proliferation and tumour growth." (PMID 36949044, 2023).
tumor (continued). "Correlation analysis of the IHC score with clinicopathologic parameters showed that YBX1 expression was correlated with Ki67 status (P = 0.037) and age (P = 0.041), but not tumor size (P = 0.162), E-cad status (P = 0.498) or lymph node metastasis status (P = 0.404)." (PMID 37370092, 2023). "However, YBX1 expression was not statistically significant with tumor stage (tumor stage III and IV vs tumor stage I and II; OR = 0.61, p = 0.406; ORadj = 0.64, p = 0.465), although it was significantly compared with normal tissues." (PMID 35861369, 2023). "Whole transcriptome analysis of YBX1-knockdown SCC25 (–YBX1) compared to SCC25 parental (+YBX1) cells showed enrichment for genes involved in the suppression of G2/M checkpoint and ribosomal biogenesis, and activation of apoptosis and anti-tumour inflammatory responses." (PMID 36949044, 2023). "We also revealed the unrecognized relationship between RNF8 and neurodegenerative diseases or tumor-infiltrating immune cells, and validated the direct binding between RNF8 and YBX1, and showed that RNF8 catalyzed the ubiquitination of YBX1, showing that RNF8 might be a crucial regulator of YBX1." (PMID 35831895, 2022). "In addition, functional experiments performed in vitro demonstrated that circ-SAR1A suppression caused a decrease in cell growth and invasion, by circ-SAR1A sponging miR-382, which targets YBX1 and reduces its expression, promoting RCC tumor growth and invasion." (PMID 35813211, 2022). "A previous study demonstrated that circFOKX2 not only interacts with YBX1 and hnRNPK to elevate the expression of the oncogenes NUF2 and PDXK but also functions as a sponge for miR-942 to upregulate the expression of ANK1, GDNF, and PAX6, which contribute to tumor progression in PDAC." (PMID 34419070, 2021). "Our results on tissue micro arrays (TMAs) are strengthened further, since staining of full section tumor tissues did not reveal significant expression heterogeneity, whether it is intratumoral or at the invasion front, for both YBX1 antibodies." (PMID 26779809, 2016). "However, tumour weight did not significantly differ between –YBX1 and +YBX1 xenografts." (PMID 36949044, 2023). "Furthermore, tumor cells seeded in a low concentration of collagen gels acquired TIC-like phenotypes and revealed enhanced resistance to chemotherapeutic agents, which was dependent on an integrin β1 (ITGB1)/Y-box Binding Protein 1 (YBX1)/Secreted Phosphoprotein 1 (SPP1)/NF-κB signaling pathway." (PMID 34758833, 2021). "In this study, knockdown of YBX1, especially when combined with the ferroptosis inducer FIN56, significantly reduced the tumour volume without affecting the body weight of the xenograft mice." (PMID 40088428, 2025). "Meanwhile, transfection of NLS-YBX1 into GSDME−/− AsPC-1 and PANC-1 cells rescued the resistance to trypsin and chymotrypsin; however, the transfection of NLS-GSDME into YBX1−/− tumour cells did not have such an effect." (PMID 35292781, 2022). "In addition, in YBX1 knockout tumour cells, replenishment of NLS-YBX1 but not NES-YBX1 upregulated MUC1 and MUC13." (PMID 35292781, 2022).
infection (25 papers, 2008 to 2025). The state of being infected such as from the introduction of a foreign agent such as serum, vaccine, antigenic substance or organism. "The results indicated that CHIKV RNA levels dramatically increased from 6 to 24 h post-infection in control HeLa cells, whereas they were only minimally increased in YBX1-deficient cells from 6 to 24 h post-infection." (PMID 39745458, 2025). "At 12 h post-infection, YBX1 formed bigger nsP3-GFP overlapping aggregates that were mostly localized in the cytoplasm." (PMID 39745458, 2025). "To understand the mechanistic basis for our previous studies on the requirement of YBX1 for DENV productive infection, we abolished its expression in Huh7 cells by using CRISPR-Cas9 genomic editing." (PMID 35189699, 2022). "YBX1 knockdown cells were established via lentiviral infection and subjected to adhesion, transwell migration, and invasion assay." (PMID 31481087, 2019). "Western blot analysis of lysates derived from FLUBV-infected A549s revealed that, from a selected subset of B/NS1 interactors, only YBX1 levels appeared to be upregulated at late times post-infection relative to the other host factors." (PMID 28869005, 2017). "During infection, however, we show that stress granule formation is inhibited and YBX1 remains cytoplasmic, whereas Npro redistributes to the replication complex after infected cells are stressed." (PMID 24965446, 2014). "Taken together, these experiments suggest that YBX1 may act as a scaffold for assembly of vRCs upon infection of alphaviruses." (PMID 39745458, 2025). "Although we cannot formally rule out indirect effects mediated by alterations of host gene expression by YBX1 depletetion, physical interactions of YBX1 with vRNA and capsid, and YBX1 localization to DENV assembly sites favor a direct role for YBX1 on DENV infection." (PMID 35189699, 2022). "As a first step to elucidate the function of YBX1 during DENV replication cycle, we studied its cellular localization upon infection." (PMID 35189699, 2022). "Validation studies in authentic infection models revealed a robust decrease in HBV cccDNA levels following silencing, providing proof-of-concept for the importance of YBX1 in the early steps of the HBV life cycle." (PMID 36591611, 2022). "In contrast, SG formed after infection with SINV wild type strain AR339 condensed into a single, large perinuclear granule, which also localised with host RNA binding proteins YBX1 and TIA1." (PMID 31905741, 2019). "A similar involvement of YBX1 in the FLUBV replication cycle remains to be determined, as does the function of YBX1 protein upregulation and its interplay with B/NS1 during the course of infection." (PMID 28869005, 2017). "Functional analyses on infection with HBV showed a marked decrease in the levels of HBV markers in YBX1-KO HepG2-NTCP cells compared with HepG2-NTCP not related to cell viability." (PMID 36591611, 2022). "Similarly, during infection with the retroviruses human immunodeficiency virus (HIV) and mouse mammary tumor virus (MMTV), YBX1 is required for virus production." (PMID 35189699, 2022). "For example, it is interesting that SARS-CoV-2, unlike other coronaviruses, has strong enrichment for binding motifs of YBX1, which has been experimentally validated to bind to SARS-CoV-2 RNA and supports infection by other viruses, including Dengue Virus, Influenza, and HIV." (PMID 35891416, 2022). "Similarly, during infection of the recombinant SINV mCherry.capsid, the virus capsid redistributed with YBX1 and TIA1 and also with VCP and G3BP1 into a single perinuclear granule." (PMID 31905741, 2019). "YBX1 stable knockdown RCC cell lines ACHN and A498 were established via lentiviral infection." (PMID 31481087, 2019). "This suggests that since YBX1 is not recruited to the replication complex during infection, it is not required for viral replication, but it may have an important function bound to Npro at sites of viral genome translation in the cytoplasm." (PMID 24965446, 2014).
neurological disease (4 papers, 2023 to 2025). "In summary, YBX1 plays a crucial role in nervous system development and function, contributing to both embryonic brain development and the regulation of inflammatory responses and epigenetic modifications associated with neurological disorders." (PMID 40799245, 2025). "YBX1 plays a crucial role in neurological disorders, influencing the development and function of the nervous system." (PMID 40799245, 2025). "The minimal overlap regions for CNV deletions containing YBX1 and YBX3 include loci beyond the gene of interest that are associated with monogenic neurological disorders and other diseases in humans." (PMID 39423228, 2024). "However, unlike the loci surrounding YBX1, none of the loss of function intolerant loci around YBX3 are known to cause monogenic neurological disease." (PMID 39423228, 2024).